PDPN (podoplanin)
Diseases named in the same sentence as PDPN in open-access papers (continued):
Sharing a sentence is not in itself a finding about the gene and the disease.
adenocarcinoma (23 papers, 2007 to 2025). A common cancer characterized by the presence of malignant glandular cells. "Further, PDPN-targeting siRNA suppressed also the effect of macrophage co-culture on adenocarcinoma cell growth." (PMID 40842027, 2025). "This phenomenon was confirmed among surgically resected human tumors in which the proliferation of adenocarcinoma cells was significantly higher in the case of podoplanin (+) CAFs than in the podoplanin (−) CAFs." (PMID 33445709, 2021). "Adenocarcinoma cells in the cases with PDPN-positive cases showed significant higher positive ratio for Geminin than in the cases with PDPN-negative CAFs (9.2% vs 2.5%, p < 0.01)." (PMID 25909164, 2015). "After sensitivity analysis excluding studies with low REMARK scores, two scores for podoplanin (OS/DSS > Univariate > All histology and OS/DSS > Univariate > adenocarcinoma only) remained unchanged." (PMID 33580106, 2021). "Generally, the expression of PDPN on CAFs is associated with poor prognosis: for example, one study found that invasive adenocarcinomas in the lung had PDPN+ fibroblasts, while non-invasive cases were all negative for PDPN staining." (PMID 22988448, 2012).
inflammation (7 papers, 2015 to 2022). Aberrant reaction of the microcirculation characterized by movement of fluid and leukocytes from the blood into extravascular tissues. "During ear inflammation in mice, induction of podoplanin+ stromal cells is dependent on myeloid cells, since depletion of CD11+ Gr1+ cells using monoclonal antibodies significantly reduces podoplanin+ cells." (PMID 34122434, 2021). "The mean podoplanin immunoreactivity score was 213.0000 in the acute placental inflammation group and 255.8824 in the control group." (PMID 31578434, 2019). "Taken together, these data suggest that the platelet CLEC-2-podoplanin signaling axis regulates the severity of lung inflammation in mice and is a possible novel target for therapeutic intervention in patients at risk of developing ARDS." (PMID 28839100, 2017). "In contrast to findings of persisting lymphatic vessels in a model of chronic airway inflammation, we found that eight weeks after cessation of Ang II both Podoplanin mRNA and protein expression were back to control levels." (PMID 26061812, 2015). "D2-40 antibodies recognizing podoplanin can detect lymphatic endothelium, and D2-40+ lymph vessel proliferation can be helpful for distinguishing between sarcoidal and other chronic/fibrous inflammations in the heart." (PMID 35011991, 2022).
lung (5 papers, 2010 to 2025). "Furthermore, supporting evidence in regard to the axis present in LSCCs was obtained from similar experiments using H157 cells, another lung SCC cell line expressing endogenous podoplanin." (PMID 21034514, 2010).
bacterial infection (2 papers, 2023 to 2025). "In summary, we propose a model for the ADAP-dependent LPS-induced surge of PDPN to form a PDPNhi PM subset as a critical response of macrophages to bacterial infection." (PMID 39903516, 2025).
neurodegenerative disease (2 papers, 2022 to 2025). A disorder of the central nervous system characterized by gradual and progressive loss of neural tissue and neurologic function. "Interestingly, we found a greater number of BST2, HLA-E, PD-L1, and PDPN positive GFAP+ astrocytes in AD post-mortem brains compared to brains from non-symptomatic individuals, warranting further investigations on the roles that these markers play in neurodegenerative disease." (PMID 35592112, 2022).
neurological disorders (2 papers, 2022 to 2023). "Podoplanin expression is upregulated in different cell types including choroid plexus epithelial cells, glial cells, as well as periphery infiltrated immune cells during brain development and neurological disorders." (PMID 36176432, 2022).
tumours of the central nervous system (2 papers, 2007 to 2010). "However, because of its widespread expression in normal tissue, podoplanin has been found of limited use for the diagnosis of CNS tumours." (PMID 17179989, 2007).
benign tumors (1 paper, 2014). "Podoplanin expression has been detected in epithelial cells of developing tooth germ and in odontogenic epithelium of benign tumors." (PMID 25480364, 2014).
PDPN also shares sentences with these, for which no sentence is quoted: leukoplakia (6 papers); Gastrointestinal tumors (5); sarcoma (5); skin cancer (4); diffuse large B-cell lymphoma (3); neuroendocrine carcinoma (3); pulmonary fibrosis (3); vasculopathy (3); dysgerminoma (2); embryonal carcinoma (2); ependymal tumor (2); follicular adenoma (2); glomerulosclerosis (2); head and neck cancer (2); head and neck neoplasm (2); hemangioblastoma (2); insulinoma (2); liver cirrhosis (2); nephropathy (2); salivary gland tumors (2); spindle cell neoplasm (2); acute myeloid leukemia (1); adenoid cystic carcinoma (1); adenomyosis (1); adenosquamous carcinoma (1); adrenocortical carcinoma (1); AIDS (1); ameloblastoma (1); anaplastic astrocytoma (1); anaplastic large cell lymphoma (1).
A further 106 diseases each share a sentence with PDPN in 1 paper.